GSTM1 (glutathione S-transferase mu 1)
Diseases named in the same sentence as GSTM1 in open-access papers (continued):
Sharing a sentence is not in itself a finding about the gene and the disease.
asthma (continued). "GSTM1 (OR 3.17, 95%CI 1.65, 6.12) and GSTT1 (OR 2.62, 95%CI 1.41, 4.87) null genotypes were associated with risk of asthma." (PMID 36250015, 2022). "GSTM1 (OR 3.49, 95%CI 1.91, 6.38) and GSTT1 (OR 6.66, 95% CI 3.55, 12.52) null genotypes were associated with risk of asthma." (PMID 36250015, 2022). "Adults and children with Glutathione S-Transferase Mu 1 (GSTM1) null genotypes have reduced glutathione-S-transferase enzyme activity and are at increased risk of developing asthma when exposed to O3." (PMID 32867076, 2020). "In a study at 504 children and adolescents with asthma aged between 3 and 21 years, children exposed to SHS and with the GSTP1 polymorphism GG (Val105Val) at nucleotide 1695 or null for the GSTM1 gene were more prone to asthma." (PMID 32380770, 2020). "Prenatal TSE significantly increased the prevalence of childhood asthma in null-GSTM1 children relative to those with positive GSTM1." (PMID 25328891, 2014). "Prenatal TSE significantly increased the prevalence of childhood asthma in children with the GSTM1 null genotype (P = 0.002, OR: 2.337, 95% CI: 1.370–3.985) compared with those with positive GSTM1 (P = 0.550)." (PMID 25328891, 2014). "Next, the relationship between prenatal TSE and childhood asthma in children with the GSTM1 null or positive genotype was analyzed." (PMID 25328891, 2014). "Asthma is believed to have a strong genetic background, and hundreds of genes have been identified to be related with asthma, including GSTM1, IL10, CTLA-4, SPINK5, LTC4S, IL4R, and ADAM33." (PMID 24790987, 2014). "There is evidence of the influence of interactions between GSTM1 and some environmental pollutants on asthma and airway obstruction." (PMID 24613990, 2014). "The aim of the current study was to detect the presence of an association between GSTM1 and GSTT1 polymorphisms and asthma, atopy or asthma severity." (PMID 24559168, 2014). "Among these 591 children, 138 (23.4%) had physician-diagnosed asthma at 6 years of age, and 347 (58.7%) were null-GSTM1." (PMID 25328891, 2014). "Few and contradictory data are available on the association between asthma development and GSTT1 and GSTM1 polymorphisms in different ethnic groups." (PMID 24559168, 2014). "The results of systematic reviews and meta-analyses of the effects of GSTM1 on asthma are also controversial." (PMID 25328891, 2014). "Polymorphisms in genes related to oxidative stress (NQO1, GSTM1, and GSTP1) have been associated with increased risk of asthma." (PMID 24465030, 2014). "This study evaluated 8 of these genes (IL4, IL13, TNF-α, HLA-DRB1, HLA-DQB1, FCER1B/MS4A2, CD14, ADAM33) as well as 3 glutathione-s-transferase genes (GSTM1, GSTP1, and GSTT1) for association with asthma/allergy among urban-residing African Americans." (PMID 21320344, 2011). "GSTM1 haplotypes CCG and CGC corresponding to SNPs rs17672, rs412543, and rs3815029, showed contrasting direction of associations with asthma." (PMID 21320344, 2011). "For example, the absence of the GSTM1 gene was associated with asthma in Europe, Africa, and Latin America, while GSTT1 deletion was linked to a higher asthma risk in Asian and Russian populations." (PMID 39594473, 2024). "Evidence for GSTM1 interaction (p < 0.05 for a range of asthma and wheezing outcomes)." (PMID 36250015, 2022). "A Taiwanese longitudinal birth cohort study (n = 591 children, 138 asthmatics at age 6) found that the GSTM1 null genotype could have a gender-specific effect on the development of asthma." (PMID 32380770, 2020). "Childhood-onset asthma risk has been shown to differ by GSTM1 genotype in relation to both maternal smoking in pregnancy and childhood ETS exposure, with effects largely restricted to children with GSTM1 null genotype." (PMID 31921716, 2019). "We investigated whether the GSTT1, GSTM1 and GSTP1 gene polymorphisms modified the associations between TRAP exposure during the first year of life and asthma, wheeze and hay fever in adolescence." (PMID 27043549, 2016).
asthma (continued). "Carriers of GSTT1 null and GSTM1 non-null mutations when exposed to TRAP had an elevated risk of asthma and wheeze at 12 years." (PMID 27043549, 2016). "Our findings suggest that the association between TRAP exposure during the first year of life and early adolescent current asthma and wheeze may be modified by GSTT1 and GSTM1 gene polymorphisms." (PMID 27043549, 2016). "It remains unclear whether the GSTM1 genotype interacts with tobacco smoke exposure (TSE) in asthma development." (PMID 25328891, 2014). "Functional studies on the role of GSTM1 in asthma are limited." (PMID 25328891, 2014). "The association between the GSTM1 null genotype and asthma development is not well established in the current literature." (PMID 25328891, 2014). "Based on the present findings, the GSTM1 null genotype in girls may be a protective factor against childhood asthma development and IgE level." (PMID 25328891, 2014). "Comparison of our results with other studies indicates that GSTT1 and GSTM1 null genotypes were not universally associated with the asthma phenotypes." (PMID 24559168, 2014). "Furthermore, a multivariate logistic regression analysis of childhood asthma in children with the GSTM1 null or positive genotype was performed to adjust for other demographic data, such as gender, prematurity, and maternal and paternal atopy." (PMID 25328891, 2014). "In particular, the GSTM1 null genotype is a protective factor against asthma in girls without prenatal TSE but becomes a risk factor for asthma with prenatal TSE." (PMID 25328891, 2014). "This study demonstrates that the GSTM1 null genotype could have a bipolar effect on childhood asthma development, depending on gender and prenatal TSE." (PMID 25328891, 2014). "Glutathione S-transferase (GST) M1 enzyme product that is involved in detoxification of both reactive tobacco metabolic intermediates and reactive oxygen species (GSTM1) null genotype has been shown to modify the effects of fetal tobacco smoke exposure on childhood asthma and wheezing." (PMID 25110663, 2014). "DNA sequence variants in the GSTP1 Ile105Val locus, GSTM1 null, and GSTT1 null may contribute to susceptibility to oxidative stress and airway inflammation, which are key processes in asthma pathogenesis." (PMID 23357926, 2013). "Maternal antioxidant gene polymorphisms (GSTP1 and GSTM1, GSTT1) have been regarded as specific risk factors for asthma in the offspring and may modify the relationship between prenatal acetaminophen exposure and childhood asthma." (PMID 22272211, 2012). "GSTM1 rs412543 C carriers were almost 3 times as likely to have asthma compared to individuals without the C allele." (PMID 21320344, 2011). "In this study, we did not observe significant associations of GSTM1 or GSTP1 polymorphisms with asthma either alone or in combination with NQO1 SNPs." (PMID 20049212, 2009). "We assessed whether polymorphisms of GST genes (GSTM1, GSTT1, and GSTP1) are associated with asthma and atopy among Tunisian children." (PMID 17497028, 2007). "Carriers of GSTM1 and GSTT1 null genotypes may be more susceptible to asthma." (PMID 36250015, 2022). "GSTs, including the isoforms GSTP1, GSTM1, and GSTT1, are multifunctional enzymes for cellular detoxification and are involved in oxidative stress pathways, among others, in the lung, and are associated, among others, with asthma and wheezing in children exposed to PTS or SHS." (PMID 32380770, 2020). "Furthermore, we found that prenatal TSE significantly increases the risk of childhood asthma in girls with the GSTM1 null genotype, but not in boys with the GSTM1 null genotype." (PMID 25328891, 2014). "Other studies have reported higher risk of non-occupational asthma for GSTM1*O subjects." (PMID 18447907, 2008). "Several case control studies have found a higher prevalence of both GSTM1 null genotypes and GSTT1 null genotypes in asthma cases, compared with controls." (PMID 36250015, 2022).
asthma (continued). "Evidence of GSTM1 interaction for in-utero (p = 0.02) and ETS (p = 0.08) for asthma outcomes, and p < 0.05 for lung function." (PMID 36250015, 2022). "Prediction of asthma by cutting off CG site methylation levels of LMO2, GSTM1, and IL10 according to the ROC curve followed by DeLong test." (PMID 31214241, 2019). "Several studies investigating the gene-environment interaction with regard to asthma development found that environmental oxidative stresses, such as tobacco smoke exposure and ozone, increased the risk of asthma in children with the GSTM1 null genotype but not in those with positive GSTM1." (PMID 25328891, 2014). "This study aimed to investigate the interactions among GSTM1 genotype, gender, and prenatal TSE with regard to childhood asthma development." (PMID 25328891, 2014). "Then, the distributions of deletion mutants of GSTM1 and GSTT1 were compared between TDI-challenge-positive (TDI-PA) and -negative (TDI-NA) asthma patients to explore the possible associations between the null genotypes and the risk for TDI-OA." (PMID 35186174, 2022). "Because GSTM1 and GSTT1 are involved in conjugation reactions and elimination of toxins to produce oxidative stress and subsequent airway inflammation, reduced GST enzymatic function can trigger asthma onset via increased oxidative stress." (PMID 35186174, 2022). "Finally, further studies to investigate the mechanisms involving the influence of LMO2, IL10, and GSTM1 genes upon PTS and childhood asthma development are needed." (PMID 31214241, 2019). "Although data are not consistent, polymorphisms of Glutathione S-transferase Mu 1 (GSTM1), Glutathione S-transferase P 1 (GSTP1), and TNF-α reportedly have associations with asthma and air pollution." (PMID 26207160, 2015). "In a longitudinal birth cohort in Taiwan, 756 newborns completed a 6-year follow-up, and 591 children with DNA samples available for GSTM1 genotyping were included in the study, and the interactive influences of gender-GSTM1 genotyping-prenatal TSE on childhood asthma development were analyzed." (PMID 25328891, 2014). "Among the children without prenatal TSE, girls with the GSTM1 null genotype had a significantly lower incidence of asthma and lower log-transformed IgE level at 6 years of age than girls with positive GSTM1." (PMID 25328891, 2014). "This study aimed to investigate the effect of the GSTM1 genotype on the relationships among prenatal tobacco smoke exposure (TSE), childhood asthma development, and allergic sensitization for different gender backgrounds in a longitudinal birth cohort study in Southern Taiwan." (PMID 25328891, 2014). "The GSTM1 null genotype is a protective factor against asthma development in girls without prenatal TSE but becomes a risk factor with prenatal TSE." (PMID 25328891, 2014). "Interactions of maternal oxidative stress genes (GSTM1, GSTP1, CAT, and MPO) with maternal prenatal exposure to air pollutants or tobacco smoke may contribute to asthma or allergic airway responsiveness." (PMID 22272211, 2012). "Another study found a small, nonsignificant decrease in forced expiratory flow at 25th to 75th percent of the FVC in children with asthma, again with a gene by environment effect; participants with no GSTM1 gene product showed a significant decrease of 6 mL/s per 10 ppb of ozone." (PMID 34389296, 2022). "Interactive effects of variants in genes belonging to the GST family (GSTP1 Ile105Val, GSTM1 deletion) with levels of different outdoor air pollutants (e.g., NO2, ozone, and particulate matter PM10 and PM2.5) have been described for childhood asthma and traffic-related air pollution." (PMID 31921716, 2019). "Similarly, another study also found that positive GSTM1 was possibly related to neutrophilic inflammation in asthma without affecting allergen-induced F2-isoprostane levels." (PMID 25328891, 2014).
asthma (continued). "In the multivariate logistic regression analysis, male gender and prenatal TSE both significantly increased the prevalence of childhood asthma in children with the GSTM1 null genotype, whereas prenatal TSE was not a significant risk factor in children with positive GSTM1." (PMID 25328891, 2014). "Different genotypes of the genes GSTM1, GSTP1, GSTT1, CYP1A1*2A and MPO also influenced the ratio between TDA in plasma and urine and therefore could predict a higher sensibility for isocyanate induced asthma in affected patients." (PMID 22016709, 2011). "We did not identify any joint effect between GSTM1 or GSTT1 and air pollutants on asthma/wheezing." (PMID 23357926, 2013).
prostate carcinoma (36 papers, 2005 to 2025). A carcinoma that arises from epithelial cells of the prostate gland. "Similar results were obtained for the Asian population, in which it was shown that the GSTM1 null genotype was associated with an increased risk of prostate cancer occurrence in China and Korea." (PMID 37819495, 2023). "GSTM1 amplifications have been reported to be marginally associated with prostate cancer risk in a Caribbean population of African descent, warranting further investigation into the function of this gene in non-European cohorts." (PMID 34068856, 2021). "Other reported genetic variations that increase African populations’ susceptibility to prostate cancer include GSTM1, GSTT1, UDP-glucuronosyltransferase, and sulfotransferase in Tunisia and Algeria." (PMID 33659210, 2020). "In their meta-analysis, Mo and co-workers 2009 found that the GSTM1 deletion increased the risk of prostate cancer in the general population, including Asians, Afro-Americans, and populations of African and Caucasian descent." (PMID 32212077, 2020). "It has been suggested that GSTM1/T1 polymorphisms are related with many diseases, such as rheumatoid arthritis, age-related macular degeneration, oral leukoplakia, prostate cancer, lung cancer, and cervical neoplasia." (PMID 27043589, 2016). "Conversely reduced expression of GSTM1 is associated with prostate cancer and leukemia and its copy number profile is correlated with prognosis." (PMID 27545843, 2016). "The null genotype of GSTM1 eliminates the gene function, leading to the inability to eliminate electrophilic carcinogens as efficiently and thus increase prostate cancer risk." (PMID 26416453, 2015). "The present meta-analysis from 8 studies mainly evaluated the potential role of GSTT1 and GSTM1 polymorphisms in prostate cancer susceptibility in Asian population." (PMID 26416453, 2015). "While significant association of elevated prostate cancer risk with GSTM1 deletion were found in China (OR = 1.665; 95%CI = 1.324 – .094) and Korea (OR = 1.914; 95%CI = 1.311 – 2.793) but not in Japan (OR = 0.980; 95%CI = 0.726 – 1.321)." (PMID 26416453, 2015). "Among the GSTs isoforms, the polymorphism of Glutathione S-transferase T1 and M1 (GSTT1 and GSTM1) to prostate cancer risk has become a research focus in scientific community and has drawn increasing attention." (PMID 26416453, 2015). "Then, analyses stratified by different country showed a significant association of elevated prostate cancer risk with GSTM1 deletion in China and Korea, the ORs were 1.665 (95%CI = 1.324 – 2.094) and 1.914 (95%CI = 1.311 – 2.793) respectively." (PMID 26416453, 2015). "The roles of GSTT1 and GSTM1 polymorphism in prostate cancer risk have been studied previously, but most published results are limited to western populations." (PMID 26416453, 2015). "Copy number of GSTT1 and combined GSTM1/GSTT1 appear to be associated with prostate cancer risk in our population study with gene dose relationship." (PMID 25198353, 2014). "We found that current or former drinkers with more than two GSTM1 or combined GSTM1/GSTT1 gene copies had a greater risk of prostate cancer than teetotalers." (PMID 25198353, 2014). "Association between copy number of the GSTM1 gene and risk of prostate cancer according to smoking, alcohol consumption, body mass index and family history of prostate cancer." (PMID 25198353, 2014). "According to the adjusted model GSTM1 carriers were at higher risk of prostate cancer (OR: 1.31, 95% CI: 1.01–1.71) than men with the homozygous GSTM1 deletion." (PMID 25198353, 2014). "In summary, our study suggests that copy number of GSTT1 and combined GSTM1/GSTT1 copy number are associated to prostate cancer risk in men of African descent with gene dose relationship." (PMID 25198353, 2014). "We also identified a possible association between GSTM1 null polymorphism and prostate cancer biochemical recurrence risk with borderline significance (HR = 1.29, 95%CI = 0.97–1.71)." (PMID 24086370, 2013).